IRF3 (interferon regulatory factor 3)
Diseases named in the same sentence as IRF3 in open-access papers (continued):
Sharing a sentence is not in itself a finding about the gene and the disease.
viral infection (continued). "Other pathways that can activate A3A and A3B include the type-I IFN pathway, which signals through STAT transcription factors, and IRF3, which is activated as part of the innate immune response to viral infection." (PMID 40323013, 2025). "Mitochondrial antiviral signaling (MAVS) was first discovered as an activator of NF-κB and IRF3 in response to viral infection in 2005." (PMID 40040697, 2025). "The IRF3 activation is considered the main regulator of IFN I in a viral infection, and this allows this protein to be transferred to the cell nucleus, binding to the IFN promoter and finally initiating its transcription." (PMID 40906234, 2025). "It has been shown to inhibit NF-κB and IRF3 signaling pathways, both of which play critical roles in orchestrating effective immune responses against viral infection." (PMID 41477199, 2025). "AMPK is a potential candidate, as it has been shown to phosphorylate TBK1 at Ser511 in response to viral infection, facilitating downstream IRF3 recruitment and innate immune activation." (PMID 41282122, 2025). "The underlying mechanism was that PDCD10 disrupted the formation of a complex between VISA and IRF3 during viral infection." (PMID 41296880, 2025). "Viral infection activates the transcription factors IRF3 and NF-κB, which induce type I interferon (IFN) and antiviral innate immune responses." (PMID 39702801, 2025). "DYRK4 acts as a scaffold protein to recruit TRIM71 and LUBAC to IRF3, thereby increasing its linear ubiquitination, maintaining IRF3 stability and activation during viral infection, and promoting the IRF3-mediated antiviral response." (PMID 39702801, 2025). "Immunoblot analysis demonstrated that AGO2 deficiency significantly increased the phosphorylation of IRF3 and STAT1 upon virus infection." (PMID 40949099, 2025). "RIG-I activates downstream signaling pathways, including those involving MAVS (mitochondrial antiviral signaling protein) and the NF-κB and IRF3 transcription factors, to orchestrate the host’s defense against viral infections." (PMID 40214229, 2025). "Given the ubiquitous role of type I IFNs in the host innate immune defense against viral infection, regulatory mechanisms governing IRF3 activation are expected to operate independently of cell type and tissue origin." (PMID 40298378, 2025). "While mammalian DDX56 directly interacts with IRF3 to block its nuclear translocation during viral infection, our study reveals a distinct regulatory mechanism in teleost fish." (PMID 41217109, 2025). "The study found that lncBST2-2 is significantly upregulated by various viral infections through the IFN/JAK/STAT signaling pathway and promotes innate immune responses to viral infections by targeting IRF3." (PMID 40285022, 2025). "Irf3 is rapidly activated during the early stages of viral infection, while irf7 primarily amplifies the interferon response, sustaining the immune reaction." (PMID 40244096, 2025). "Upon virus-infection IRF3 binds robustly across C/I loci, weakly on C/II, and is slightly (HL) or not recruited (NM) on C/III." (PMID 40131776, 2025). "Upon activation by viral infections or danger signals, IRF3, 5, and 7 proteins undergo nuclear translocation, enabling DNA interaction and transcriptional regulation of immune response genes (right)." (PMID 39977406, 2025). "Viral infection stimulates the nuclear translocation of RelA NF-κB heterodimers from their cytoplasmic IκBα-inhibited latent complexes and also activates Interferon regulatory factor 3 (IRF3)." (PMID 40964367, 2025). "In contrast, SIRT1 deficiency leads to hyperacetylation of IRF3/IRF7, suppressing innate immunity and increasing susceptibility to viral infections." (PMID 40166469, 2025). "This study establishes important roles for DYRK4 in virus-triggered IRF3 activation, IFNβ induction, and the cellular antiviral response and provides a mechanistic explanation of how IRF3 remains stable before and after viral infection." (PMID 39702801, 2025).
viral infection (continued). "The IRF3 gene has been employed in current studies as an important molecular marker against viral infections." (PMID 40831556, 2025). "Conversely, viral infections can impede the phosphorylation, dimerization, or nucleation processes of IRF3, thereby impeding the normal transmission of signals." (PMID 39601590, 2025). "As a pivotal member of the RLR pathway, TRAF3 is essential for activating the MAVS/TBK-1/IRF3 signaling pathway in response to viral infection." (PMID 39058724, 2024). "The interaction of MAVS with TRAF3/6 plays a crucial role in various viral infection mechanisms by activating the IRF3, IRF7, and NF-kB pathways." (PMID 38995016, 2024). "The activation of IRF3 is initiated by various signals, including viral infection, bacterial infection, and cellular stress." (PMID 38578631, 2024). "Viral infections, for instance, activate PRRs, leading to the induction of transcription factors nuclear factor kappa-B (NF-κB) and Interferon regulatory Factor 3/7 and subsequently triggering apoptosis via NF-κB signaling." (PMID 38666826, 2024). "Transcript expression levels of several members of the IRF family (e.g., IRF3, 5, and 7) are upregulated following viral infections." (PMID 39211041, 2024). "Upon activation, IRF3/7 and NF-κB translocate to the nucleus to trigger the transcription of a variety of cytokines, which are responsible for resisting virus infection." (PMID 39211800, 2024). "IRF3 is known to activate the expression of type I interferons as well as interferon-responsive genes upon viral infection." (PMID 38730323, 2024). "During viral infection, cytosolic IRF3 is induced to form a complex with BAX, which then translocates to the mitochondria leading to apoptosis." (PMID 38459007, 2024). "IRF3 is a transcription factor activated upon viral infection, leading the transcription of ifn-I genes." (PMID 38921776, 2024). "During virus infection, dsRNA replication intermediates are sensed by cytosolic Rig-like receptors and activate IRF-3 and NF-kB transcription factors to upregulate IFN, cytokines, and antiviral factors that can induce apoptosis." (PMID 39772220, 2024). "Since IRF3 becomes activated upon viral infection and then translocates to the nucleus to induce antiviral innate immunity." (PMID 39362857, 2024). "SNAI1 is a direct target of IRF3, and viral infection as well as intracellular Poly I:C treatment have been shown to induce SNAI1 and SNAI2 expression." (PMID 39159817, 2024). "The canonical models of type-I IFN production state that IRF3 is activated prior to IRF7 in viral infections that trigger TLRs or RIRs." (PMID 39702382, 2024). "ZAP, an antiviral effector ISG that inhibits replication of filoviruses, retroviruses, and alphaviruses (91, –, 93), is induced by viral infection and dsRNA via TLR3, RIG-I/MDA5, and IRF3 axis in type-I and type-III IFN signaling-deficient cells." (PMID 39302126, 2024). "When stimulated by 5′ppp dsRNA, chickens cannot produce type I interferons in time to fight viral infection, but ducks can rapidly increase the expression of Src, activate NF-κB and IRF3, and eventually produce IFN-β." (PMID 39202404, 2024). "Zebrafish tbk1 kinase activity and tbk1-mediated irf3 phosphorylation play an important role in defence against viral infection." (PMID 38739631, 2024). "Lastly, TRAF3 has been shown to be a critical component in the activation of IRF3 during the innate immune response to viral infections." (PMID 38589899, 2024). "IRF3, a crucial component of the innate immune response, was responsible for detecting and reacting to foreign antigens, thereby helping to prevent viral infections." (PMID 38999981, 2024). "RNA viruses such as Sendai virus (SeV) and VSV trigger the activation of TRIM21, interacting with MAVS and catalyzing MAVS polyubiquitination, activating IRF3, and suppressing viral infections." (PMID 39335111, 2024).
viral infection (continued). "It appeared that the dynamics of IRF3 hydroxylation during viral infection was due to changes in the hydroxylase activity of EGLN1 during viral infection." (PMID 38670937, 2024). "There are many reviews of IRF3 function during viral infection, but few recent reviews of IRF3 function in response to endotoxin." (PMID 38375470, 2024). "In response to viral infection, IKKε acts as a key molecule in the regulation of innate immunity by activating IRF3 or IRF7." (PMID 38315275, 2024). "Here, we found that IRF3 is hijacked and sequestered into EBOV IBs by viral infection, which demonstrates that viral IBs are utilized for IRF3 compartmentalization." (PMID 38285487, 2024). "We next assessed the effect of ADAP deficiency on the activation of IRF3 and TBK1, the key downstream signaling molecules of RIG-I in macrophages upon LPS stimulation or viral infection." (PMID 38776321, 2024). "The modulation of NF-κB and IRF-3 expression by OMT post-TLR3 silencing aligns with the broader understanding of TLR3′s involvement in viral infections and immune regulation." (PMID 38731436, 2024). "Consistently, the nuclear translocation of IRF3 was enhanced in ATG7 knockdown A549 cells compared with control cells following viral infection." (PMID 38227600, 2024). "Viral infection induces targeted autophagic degradation of HDAC10 resulting in increased phosphorylation of IRF3 and enhanced interferon response." (PMID 38660307, 2024). "Although it has been reported that IRF3 stimulates cell apoptosis independently of its DNA-binding domain, the functional implication in viral infection remains largely unclear." (PMID 39362857, 2024). "Interferon regulatory factor 3 (IRF3) is an interferon regulatory transcription factor that plays an important role in coordinating the innate immune response to viral infection." (PMID 39551951, 2024). "Upon virus infection, nuclear translocation of IRF3 was inhibited by the S97D substitution in IRF3 (which imitates the phosphorylated condition) in IRF3- and IRF7-knockout cells." (PMID 38396775, 2024). "Various irfs (e.g., irf1, irf2, irf3, irf4b, irf7, irf9, and irf10) were previously found upregulated with poly(I:C) or viral infection in teleost species." (PMID 39211041, 2024). "Recent studies have shown that the BAs receptor TGR5 promotes type I interferon production through the AKT/IRF3 signaling pathway during virus infection." (PMID 39220861, 2024). "Then the IFN-I response promoted by PBLD after knockdown of IRF3 using siRNA during virus infection was assessed." (PMID 39362857, 2024). "TBK1 is the crucial kinase in innate immune system, it stimulates transcription factor IRF3 and NF-κB in multiple signaling pathways during viruses infection to induce interferon and inflammatory factor expressions." (PMID 38449860, 2024). "Firstly, IRF3, upon activation, stimulates the expression of antiviral genes in innate immunity, which plays an important role in defending against viral infections." (PMID 39362857, 2024). "Pattern recognition receptors activate IRF3 and NF-κB during viral infections, initiating downstream signals to interfere with viral life cycle." (PMID 39706834, 2024). "During viral infection, viral DNA and RNA activate IRF3/IRF7, which activates IFNA/IFNB gene transcription." (PMID 37264110, 2023). "Collectively, the most valuable finding from our study is that targeting BLK offers a protective function against viral infection by enhancing IRF3 activation and IFN production." (PMID 37871014, 2023). "Although vertebrate IRF3s exhibit a “one to one” orthologous relationship to each other, fish IRF3 is a virus- and IFN-induced protein, and instead, mammalian IRF3 is constitutively expressed even under viral infection." (PMID 36902023, 2023).
viral infection (continued). "The well-characterized importin alpha (IMPA) and importin beta (IMPB) nuclear import pathway plays a crucial role in the innate immune response to viral infection by mediating the nuclear import of transcription factors such as IRF3, NFκB, and STAT1." (PMID 38201275, 2023). "The expression of IRF7 in most cells is low, while IRF3 is ubiquitously expressed triggering the phosphorylation of IRF3 upon viral infection in nearly all cell types." (PMID 37333411, 2023). "PGAM5 regulates the activity of inflammasome and caspase 1 in BMDMs and contributes to IFN-β production in response to viral infection by promoting the TBK1 (TANK-binding kinase 1)/IFN regulatory factor 3 (IRF3) signaling pathway." (PMID 37771598, 2023). "The transcription factor interferon regulatory factor 3 (IRF3) plays an important role in host defence against viral infections." (PMID 36817435, 2023). "While the first two pathways are generally related to cell signaling and general cell metabolism functions, the latter (IRF3 pathway) is one of the central pathways in regulating type 1-interferon during bacterial and viral infections." (PMID 37664632, 2023). "It has been reported that STING activates both IRF3 and NF-κB, which mediate immune defense against tumors and viral infections." (PMID 36980689, 2023). "IRF1 and IRF3 upregulate transcription of certain ISGs in IFN-independent manners during virus infection." (PMID 37197656, 2023). "The transcriptional levels of TBK1 are stimulated by viral infection at 9 h post-infection and subsequently allow the accumulation of IRF3 and NF-κB transcripts." (PMID 37764935, 2023). "Upon viral infection, a series of cellular pathways are activated subsequently to promote the translocation of phosphorylated IRF3 or IRF7 into the nucleus and initiate the transcription of type I interferon genes by attaching to IFN-α/β promoters." (PMID 37090696, 2023). "As one of the DNA sensors, interferon (IFN)-γ inducible protein 16 (IFI16) play a major role in response to virus infections through activating the canonical STING/TBK-1/IRF3 signaling pathway." (PMID 37410794, 2023). "Viral infection can be detected by pattern recognition receptors (PRRs) in host cells that trigger the activation of IRF3 and IRF7, thereby inducing the production of type I IFN and IFN-stimulated genes (ISGs)." (PMID 37833891, 2023). "Upon viral infection, IRF3 undergoes phosphorylation-dependent dimerization, leading to the production of IFNs and other cytokines." (PMID 38250078, 2023). "During viral infection, IRF3 and NF-κB can be phosphorylated by the protein kinase TBK1 and subsequently translocated to the nucleus as activated transcription factors." (PMID 37222520, 2023). "Future studies involving pathway-specific IRF3 mutants can be utilized to elucidate the role of RIKA in diseases beyond viral infection." (PMID 37515265, 2023). "In this study, we identified BLK as a positive modulator of IRF3-dependent antiviral signaling in response to viral infection." (PMID 37871014, 2023). "This process promotes the production of IRF3-initiated antiviral type I interferons (IFNs) by preventing IRF3 proteasomal degradation, thereby enhancing host defense against viral infection." (PMID 37996849, 2023). "Studies have reported that IRF3 and NF-κB are required for protecting host cells against viral infection." (PMID 37711616, 2023). "Viral infection triggers the activation of transcription factor IRF3, and its activity is precisely regulated for robust antiviral immune response and effective pathogen clearance." (PMID 37871014, 2023). "Other genes significantly up-regulated in the hsa05203 pathway were IRF3 and IRF7, which encode interferon regulatory factors that play key roles in the innate immune response to virus infection and the transcriptional activation of type-I IFN genes." (PMID 38003837, 2023).
viral infection (continued). "DNA sensors, including IFI16, DDX41, and cyclic GMP-AMP (cGAMP) synthase (cGAS), play a major role in response to virus infections through activating the canonical STING/TBK-1/IRF3 signaling pathway." (PMID 37410794, 2023). "Under normal conditions, IRF3 remains inactive in the cytoplasm; however, during viral infection, it is activated by phosphorylation, resulting in a major antiviral defense." (PMID 37376674, 2023). "Ser396 is a phosphorylated target after virus infection and plays an important role in IRF3 activation." (PMID 37022262, 2023). "Aside from STAT1, the nucleocytoplasmic trafficking of other key innate immunity signal transducers, such as IRF3 and NF-κB (p50/p65), is also critical for the activation of host innate immune response upon viral infection." (PMID 38203469, 2023). "JMJD6 plays a crucial role in recruiting RNF5 and IRF3, facilitating their translocation from the cytoplasm to the nucleus upon viral infection." (PMID 38250078, 2023). "It is known that IRF3 binds to ISRE in the human ZAP promoter during viral infection, and type I IFN has a greater effect on inducing ZAP-S expression compared to ZAP-L, possibly through transcription regulation, alternative splicing, or polyadenylation." (PMID 38133344, 2023). "Following viral infection, IRF3 nuclear translocation was also repressed in ZNF268a deficient HEK293T cells." (PMID 37926288, 2023). "IRF3 is critical for early induction of IFN expression in most cells post-viral infection; IRF7, which induces both IFNα and IFNβ expression, has functions in the antiviral activity of IFN in a later stage." (PMID 37090696, 2023). "In macrophages, the role of PP2Ac in modulating IRF3 or NFkB signaling in the setting of viral infections or Toll-Like Receptor (TLR) stimulation has been reported." (PMID 36757811, 2023). "The inactive IRF3 localized in the cytoplasm is phosphorylated and dimerized after stimulation by viral infection, which allows for its nuclear translocation and subsequent induction of IFN genes." (PMID 36537793, 2023). "CH has been shown to reduce the levels of inflammatory factors that were induced by viral infection; moreover, it suppressed the expression of IRF3/7, TBK, and IKK." (PMID 37711616, 2023). "To investigate a possible role of ORF6 in antagonizing activation in infected cells, we infected cells with WT or ΔORF6 virus for 48 h and monitored IRF3 nuclear translocation and viral infection at single-cell resolution by confocal microscopy." (PMID 37377442, 2023). "Mechanistically, D2HG produced by mutant IDH1 enhances the binding of DNMT1 to IRF3/7 promoters such that IRF3/7 are downregulated, leading to impaired type I IFN response in glioma cells, which enhances the susceptibility of gliomas to viral infection." (PMID 37880243, 2023). "The STING C-terminal tail recruits TBK1 and IRF3 to potentiate expression of IFN-I during virus infection." (PMID 37902401, 2023). "During viral infection, this IRF3-mediated shortcut in the type I IFN-mediated antiviral response enables induction of gene expression before or in the absence of IFNAR activation (9, 18, –, 20)." (PMID 37289084, 2023). "We investigated a possible interaction between optineurin and viral infection in IFNβ production because we previously showed that optineurin inhibits the activities of NF-κB and IRF3." (PMID 37352136, 2023). "In DNA or RNA viral infection defence, vertebrate IRF3 is the key transcription factor in the signalling of type I interferon-dependent immune responses." (PMID 36817435, 2023). "A previous study has shown that MAPK signaling increases the phosphorylation of TBK1 and IRF3 upon viral infection." (PMID 37833891, 2023). "While type I IFNs represent a major target of IRF3-mediated gene regulation, several reports have demonstrated that during viral infection, IRF3 also regulates expression of a subset of ISGs (9, 19, –, 21)." (PMID 37289084, 2023).